IGF1R (insulin like growth factor 1 receptor)
Diseases named in the same sentence as IGF1R in open-access papers (continued):
Sharing a sentence is not in itself a finding about the gene and the disease.
lung adenocarcinoma (continued). "In this study, we demonstrated, for the first time, that GAS5 exerts a tumor suppressive function by regulating IGF-1R expression in lung adenocarcinoma." (PMID 25925741, 2015). "Fenofibrate also significantly reduced the serum insulin and insulin-like growth factor (IGF)-1 levels, and decreased the immunohistochemical expression of IGF-1 receptor (IGF-1R), phosphorylated Akt, and phosphorylated Erk1/2 in lung adenocarcinomas." (PMID 24857924, 2014). "Here, we show that TM4SF4 is highly expressed in radiation-resistant lung adenocarcinoma cells, such as A549 and Calu-3 cells, and its expression activates cell growth, migration, and invasion via IGF1R activation." (PMID 25344917, 2014). "Here we found a positive correlation between the body mass index (BMI), blood glucose levels, reduced overall survival (OS) and the expression of Insulin-like growth factor-1 receptor (IGF1R) in the lung tumoral region of patients with lung adenocarcinoma (LUAD)." (PMID 35574343, 2022). "For instance, upregulated expressions of Notch 1 in hypoxic lung adenocarcinoma cells activate insulin-like growth factor 1 receptor (IGF1R) via binding to the IGF1R promoter directly leading to activation of Akt1, which allows the tumor cells to survive under hypoxic parameters." (PMID 32316322, 2020). "In lung adenocarcinoma, IGF-1R overexpression and Akt activation by NOTCH1 is stimulated by hypoxic microenvironment, and NOTCH1 targeting may provide a viable therapeutic approach for patients with K-Ras mutant lung adenocarcinoma." (PMID 27980227, 2017). "We tested these hypotheses further by developing our own in vitro models of crizotinib resistance using human ALK+ lung adenocarcinoma cells, studying both the effects of IGF-1R inhibition shortly after crizotinib treatment and chronic crizotinib exposure." (PMID 29066738, 2017). "In conclusion, the mutation of EGFR was associated with adenocarcinoma, smoking status, and gender and the polymorphisms of the IGF1R rs2229765 gene were associated with the L858R mutation of EGFR in female lung adenocarcinoma patients who had never smoked." (PMID 27213344, 2016). "The IGF-1R (insulin-like growth factor 1 receptor) protein level, which has been associated with resistance to EGFR-TKIs, was also analyzed to explore the potential mechanisms behind the effects of the GAS5/gefitinib combination on gefitinib-resistant lung adenocarcinoma cells." (PMID 25925741, 2015). "Therefore, we hypothesized that GAS5 may also mediate IGF-1R function to enhance the sensitivity to EGFR-TKIs in lung adenocarcinoma." (PMID 25925741, 2015). "CLDN18.1 inhibits IGF-1R/AKT and YAP/TAZ/AKT signaling pathways in lung adenocarcinoma cells, which correlates with favorable prognosis." (PMID 37438735, 2023). "Several compounds which were sensitive to mutant subtypes of lung adenocarcinoma were identified, such as inhibitors of PI3K/Akt and IGF1R signaling pathways." (PMID 35371318, 2022). "Higher glucose levels and the IGF1R/IGF1 axis promote tumor development, inhibit tumor cell death and activate glucose metabolism in human lung adenocarcinoma cells." (PMID 35574343, 2022). "In lung adenocarcinoma cells, fibulin-3 demonstrates inhibitory effects on EMT and self-renewal capacity by suppressing β-catenin through insulin-like growth factor-1 receptor (IGF1R)/phosphatidylinositide 3-kinase (PI3K)/AKT signaling pathways." (PMID 30227601, 2018). "In this study, we demonstrated that TM4SF4 is overexpressed in lung adenocarcinoma cells as a result of hypomethylation in the promoter region of the TM4SF4 gene, and it enhances activation of the IGF1R pathway and, consequently, enhances tumorigenicity." (PMID 25344917, 2014). "In summary, the microRNA, miR-133a, inhibits the expression levels of multiple oncogenic receptors, i.e., EGFR, IGF1R, and TGFBR1, and mediates cell growth and invasion in lung adenocarcinoma." (PMID 24816813, 2014).
lung adenocarcinoma (continued). "In lung adenocarcinoma cell line H1299, Trop2 over-expression decreases ERK and AKT phosphorylation, Trop2 binds to IGF-1, inhibiting its ability to activate IGF-1R and reducing the activation of AKT and ERK by IGF-1R signaling pathway." (PMID 39135109, 2024). "In addition, the CD74-NRG1 oncogenic fusion gene activates the PI3K/AKT/NF-κB pathway in lung adenocarcinoma and induces activation of the IGF-2/IGF-1R autocrine loop." (PMID 33511137, 2020). "In conclusion, this study presents the pivotal finding that low expression of SOCS2 induces invasion and metastasis of human lung adenocarcinoma cells by regulating EMT both in vitro and in vivo, which is mainly dependent on the IGF1/IGF1R-stimulated STAT3 or STAT5 pathway." (PMID 29559623, 2018). "This particular study recognised the effect of GAS5 in enhancing apoptosis due to gefitinib activity within innate EGFR tyrosine-kinase inhibitor (TKI) resistant lung adenocarcinomas (A549 cell line), through the gene regulating role of GAS5 on insulin-like growth factor 1 receptor (IGF-1R)." (PMID 28273813, 2017). "The IGF-1R signaling axis is highly activated during the early stages of lung carcinogenesis, where a role for IGF-1R signaling was demonstrated not only in primary tumor formation but also in progression to more aggressive lung adenocarcinoma." (PMID 24809702, 2014). "The lung adenocarcinoma cell line, HCC827, exhibited the greatest number of activated RTK pathways, with HER1, c-MET, and HER2 being highly activated, PI3K being moderately activated, and HER3 as well as IGF-1R being lowly activated." (PMID 22091388, 2011). "Most interestingly, the expression of SOCS2 dose dependently reduced the interaction between IGF1R and STAT3 or STAT5, indicating that SOCS2 acts as a STAT3/STAT5 inhibitor that can competitively bind to IGF1R and thus can attenuate the IGF1-induced STAT3/STAT5 activity in lung adenocarcinoma cells." (PMID 29559623, 2018). "Moreover, IGF1 could not effectively induce EMT and tumour malignant development in SOCS2-overexpressed lung adenocarcinoma cells, further indicating the critical inhibitory role of SOCS2 in the IGF1/IGF1R axis in the EMT and progression of lung adenocarcinoma cells." (PMID 29559623, 2018).
triple-negative breast carcinoma (41 papers, 2012 to 2025). An invasive breast carcinoma which is negative for expression of estrogen receptor (ER), progesterone receptor (PR), and human epidermal growth factor receptor 2 (HER2). "On the contrary, strong IGF1R expression was associated with aggressive features in triple negative breast cancer, such as high histological grade." (PMID 26449867, 2015). "The pineal hormone, in triple-negative breast cancer cells, upregulates the expression of miR-152-3p, therefore decreasing the protein levels of some of its target genes (IGF-1R, HIF-1α and VEGF) both in vitro and in vivo." (PMID 38473317, 2024). "We observed that IGF-1R, in triple-negative breast cancer tissues, is predominantly intracellular and dispersed from the plasma membrane compared with nontumor tissue." (PMID 39608716, 2024). "FAK also interacts directly with IGF1R and this interaction is critical for the growth pancreatic cancer, triple negative breast cancer, and melanoma." (PMID 34031486, 2021). "In triple-negative breast cancer, circGNB1 promoted growth and metastasis via sponging miR-141-5p to upregulate IGF1R." (PMID 34507559, 2021). "The IGF-1/IGF-1R/YAP pathway was reported to promote growth effects in triple-negative breast cancer (TNBC) cells." (PMID 34359714, 2021). "IGF1R signaling can stimulate cell proliferation and protect cell from stress in triple negative breast cancer and is regarded as a therapeutic target for treatment." (PMID 32194644, 2020). "A large portion of triple-negative breast cancer cells express IGF-1R, and activated IGF signaling promotes cell survival and proliferation." (PMID 28046018, 2017). "Here, we review relevant background and recent studies suggesting that inhibiting the IGF-1R can amplify Wnt and Notch signaling pathways in a model of triple negative breast cancer." (PMID 26106366, 2015). "The Dog appears to be a relevant naturally-occurring model of IGF1R overexpressing triple-negative breast cancer, opening the way for possible translational perspectives in the search for new therapeutic opportunities, including anti-IGF1R therapies." (PMID 26449867, 2015). "The insulin like growth factor 1 receptor (IGF-1R) is a transmembrane receptor expressed in many human cancers, including in ~35% of all triple-negative breast carcinomas." (PMID 24991539, 2014). "Furthermore, FAK activation is required for IGF1R-mediated regulation of migration and invasion in triple negative breast cancer cells." (PMID 34031486, 2021). "Preclinical studies using the Dog as a spontaneous animal model could be considered to investigate new therapies targeting IGF1R in triple-negative breast cancer." (PMID 26449867, 2015). "Current research on triple-negative breast cancer includes anti-tumor-related pathways against IGF1, promotion of tumor cell death, and targeting the IGF-1/IGF-1R signaling axis for the treatment of TNBC." (PMID 41209699, 2025). "In triple-negative breast cancer cells with high ITGB1 expression, suppressing ITGB1 enhanced IGF-1R stability and its retention at the plasma membrane, and reduced IGF-1R internalization during cell adhesion." (PMID 39608716, 2024). "IR-A, IR-B, IGF1R and IGF-II mRNA expression in a panel of triple negative breast cancer cell lines." (PMID 36920947, 2023). "MAPKAPK3, AKT3, CDK5, IGF1R, and MAPK11 are potential prognostic markers and therapeutic targets of curcumin in patients with triple-negative breast cancer." (PMID 37569854, 2023). "In triple negative breast cancer, cell growth and fokal adhesion formation are triggered by an IGF1/IGF1R/FAK/Akt/YAP signaling cascade." (PMID 34440844, 2021). "In triple-negative breast cancer cells, MZF1 activation can maintain the mesenchymal phenotype by interacting with Elk1 at the promoter region of IGF1R." (PMID 31963147, 2020). "We previously reported that IGF-1R regulates FAK signaling and EMT in triple-negative breast cancer." (PMID 29212236, 2017).
triple-negative breast carcinoma (continued). "In agreement with our previous observations in cell lines, we confirmed, by immunofluorescence, that IGF-1R is located less at the plasma membrane in triple-negative breast cancer (TNBC) tumor tissue than in nontumor tissue." (PMID 39608716, 2024).
cervical carcinoma (39 papers, 2008 to 2025). A carcinoma arising from either the exocervical squamous epithelium or the endocervical glandular epithelium. "In the present work, we observed that increasing O-GlcNAcylation promotes proliferation and invasiveness of cervical cancer cells, associated with activation of IGF1R/PI-3 kinase/Akt signaling." (PMID 35296731, 2022). "Transcriptomic profiling of blood samples drawn from cervical cancer patients identified IGF1R as a biomarker for increased risk of treatment failure." (PMID 34068918, 2021). "On the other hand, low levels of IGFBP-3 and IGF-1R mRNA in cervical scrapes were found to be associated with progression to cervical cancer." (PMID 25333772, 2014). "According to another hypothesis, overexpression of IGF-1R in cervical cancer cells may be treated as an indicator of high-risk disease and disease recurrence in the early stage." (PMID 38392069, 2024). "We also expanded the study to include another migratory cell line, HeLa cervical carcinoma cells, in which we also observed IGF-1R at the Golgi." (PMID 39608716, 2024). "The IGF-1R/PI-3K/Akt (IGF-1 receptor/Phosphatidyl Inositol-3 kinase/Akt) axis is considered an essential target for cervical cancer treatment." (PMID 35296731, 2022). "A retrospective analysis of patients with cervical cancer showed that IGF1/IGF1R signaling is involved in tumor formation and clinical outcome." (PMID 34071893, 2021). "In this work we show that IGF1R interacts with PCNA after irradiation and HU treatment in HeLa cells (cervical cancer cells) and IGF1R positive fibroblasts." (PMID 32701997, 2020). "Consistent with this, Insulin-like growth factor 1(IGF1R) is reported to promote cervical cancer development." (PMID 32655987, 2020). "To investigate the biological significance of IGF2R and IGF1R in cervical cancer cells, we analyzed six cervical cancer cell lines using gene knockdown." (PMID 31748500, 2019). "For example, the lncRNA Ras suppressor protein 1 pseudogene 2 (RSU1P2) was shown to be overexpressed in cervical cancer and to play a tumor-promoting role by acting as a ceRNA for microRNA let-7a and regulating the expression of IGF1R, N-myc, and EphA4." (PMID 28209205, 2017). "The correlation between IGF-1R expression and cervical cancer stages is also limited in early-stage cervical cancer." (PMID 25070070, 2014). "In a retrospective study of patients with early-stage cervical cancer it was shown that high overexpression of IGF-1R is an independent predictor of cervical cancer death and recurrence." (PMID 25333772, 2014). "It was pointed out that IGF-1, acting through IGF-1R, interacted with αvβ3 integrin in cervical cancer cell invasiveness and proliferation." (PMID 25333772, 2014). "IGF-1R was overexpressed in HPV-positive cervical cancer cell lines in comparison to ovarian cancer cell lines and HPV-negative cervical cell line C33A." (PMID 25333772, 2014). "We have pointed out that IGF-1, as a stimulator through IGF-1R signalling, interacted with αvβ3 integrin in cervical cancer cell invasiveness and proliferation." (PMID 18781172, 2008). "This study aims to investigate the association of IGF-1 system and clinical outcome of cervical cancer, by analysing the serum levels of IGF-1 and IGFBP-3, and tissue abundances of IGF-1R for the same patient." (PMID 18781172, 2008). "The function of IGF-1R expression in disease outcome in cervical cancer has rarely been discussed in earlier literature." (PMID 18781172, 2008). "We at first examined the expression level of IGF-1R in surgical specimens of early-stage cervical cancer by IF staining." (PMID 18781172, 2008). "Earlier we have investigated the regulatory mechanism of IGF-1R signalling and its importance in cervical cancer formation by cell lines and animal model." (PMID 18781172, 2008). "Related pathways on the synthesis, expression, ligand-receptor interaction and tyrosine-kinase activation of IGF-1R in cervical cancer deserve further clarifications." (PMID 18781172, 2008).
cervical carcinoma (continued). "Similarly, miR-10b-5p, often downregulated in cervical cancer tissues, inhibits cell proliferation, migration, and invasion by targeting insulin-like growth factor-1 receptor (IGF-1R) and Homeobox A1 (HOXA1)." (PMID 39796267, 2025). "Increased levels of IGF-1 in patients with T2DM and overexpression of IGF-1R in cervical cancer cells might activate the IGF intracellular signaling pathway, resulting in a poor prognosis." (PMID 38392069, 2024). "Indeed, several lines of evidence indicate that IGF1R plays an important role in growth and survival of cervical cancer cells." (PMID 35296731, 2022). "We therefore hypothesized that PTP1B could also play an important role in the regulation of IGF1R signaling in cervical cancer cells." (PMID 35296731, 2022). "Together, our results indicate that increased O-GlcNAcylation, by activating IGF1R/ Phosphatidyl inositol 3-Kinase (PI-3K)/Akt signaling, may participate in cervical cancer cell growth and proliferation." (PMID 35296731, 2022). "In that report, we also showed that IGF-1 induces depalmitoylation and repalmitoylation, a dynamic palmitoylation turnover, of the PM-targeted Flot-1, which facilitates prolonged activation of IGF-1R on the cell surface and hence promotes cervical cancer cell proliferation." (PMID 30631151, 2019). "Additionally, IGF1R, N-myc and EphA4 were generally expressed at a high level in 14 pairs of clinical cervical carcinoma tissue samples." (PMID 27487126, 2017). "We demonstrated that the engineered ubiquitin ligase PTB-U-box can promote the ubiquitination and degradation of IGF-1R and IR, and thus effectively inhibit in vitro and in vivo malignant behaviors of liver cancer HepG2 and cervical cancer HeLa cells that over-express IGF-1R and IR." (PMID 24970814, 2014). "Further investigation showed that small interfering RNA-mediated IGF-1R knockdown could mimic the effect of enforced miR-497 expression on the malignant phenotypes of cervical cancer cells." (PMID 25333772, 2014). "IGF-1 receptor (IGF-1R) expression level is elevated in cervical cancer cell cultures." (PMID 25070070, 2014). "(iii) The colocalisation of IGF-1 and IGF-1R in the cancerous tissues, and the lack of correlation between circulating IGF-1 or IGFBP-3, and IGF-1R overexpression in cervical cancer cells suggest likely autocrine or paracrine IGF-1 stimulation of IGF-1R signalling." (PMID 18781172, 2008). "In contrast, cervical cancer tissues clearly expressed IGF-1R protein with different amounts." (PMID 18781172, 2008). "In early-stage cervical cancer, IGF-1 system may have a paracrine or autocrine function and the adverse impacts on prognosis by IGF-1R overexpression are implicated." (PMID 18781172, 2008). "Therefore, the O-GlcNAcylation-induced up-regulation of the IGF1R/PI-3K/Akt axis observed in our study may also have important pathophysiological significance in the context of cervical cancer." (PMID 35296731, 2022). "This conclusion is supported by the following findings: (i) high-grade overexpression of IGF-1R is an independent predictor of cervical cancer death and recurrence, and when combined with elevated serum SCC Ag level could further help identify the subgroup of patients at higher death risk." (PMID 18781172, 2008). "Therefore, the application of IGF-1R overexpression may be rational to predict clinical prognosis in operable cervical cancer." (PMID 18781172, 2008). "RSU1P2, a pseudogene of Ras suppressor protein 1, is upregulated in cervical cancer and promotes tumorigenic phenotypes by sponging let-7a from IGF1R (insulin like growth factor 1 receptor), MYCN, and EPHA4 (EPH receptor A4)." (PMID 29702599, 2018). "As a result, miR-let-7c-5p/insulin-like growth factor 1 receptor/phosphatidylinositol-3 kinase/AKT serine/threonine kinase 1 (miR-let-7c-5p/IGF-1R/PI3K/AKT) and beta-catenin/snail family transcriptional repressor 2 (β-catenin/SLUG) were highlighted as potential targets against cervical cancer." (PMID 37576994, 2023).
cervical carcinoma (continued). "Although neither IGF2R nor IGF1R knockdown altered cell cycle status in cervical cancer cells, only apoptotic cells and caspase activities were significantly increased by IGF2R knockdown." (PMID 31748500, 2019). "Furthermore, we revealed that the binding of RSU1P2 to the let-7a miRNA relieved the suppression of the let-7a-targeted genes IGF1R, N-myc and EphA4, which may explain role of RSU1P2 in tumorigenesis of cervical cancer." (PMID 27487126, 2017). "Considering that IGF1R knockdown did not increase apoptosis, IGF-2–IGF1R signaling is not necessary for cervical cancer cells to survive." (PMID 31748500, 2019). "The same research group demonstrated that cervical cancer cell lines, positive and negative for HPV, differ in the type of insulin and IGF-1 receptors expressed, while SiHa cells expressed IGF-1R, IR-A and IR-B and IR/IGF-1R hybrid receptors, C33a cells expressed the IR-A only." (PMID 25333772, 2014). "Moreover, the serum level of IGF-1 or IGFBP-3 did not statistically differ between the two distinct IGF-1R overexpressions (P=0.77 and P=0.07, respectively), indicating no direct correlation between circulating IGF-1 or IGFBP-3, and IGF-1R overexpression in cervical cancer cells." (PMID 18781172, 2008).